ILDR1 (immunoglobulin like domain containing receptor 1)
Diseases named in the same sentence as ILDR1 in open-access papers:
ILDR1 is named in the same sentence as 27 diseases in open-access papers, as found by Europe PMC text mining. Sharing a sentence is not in itself a finding about the gene and the disease. The quoted sentences say what the papers report.
deafness (17 papers, 2012 to 2025). An inherited or acquired condition characterized by the complete loss of the ability to hear from one or both ears. "In this study, targeted next-generation sequencing (NGS) in two Chinese Han families identified a novel p.G141R homozygous mutation in ILDR1 as the genetic cause of the deafness." (PMID 29849566, 2018). "In this study, we reported a novel missense mutation within the ILDR1 gene associated with partial deafness, and identified partial mislocalization of the mutant angulin-2/ILDR1 protein at TCs." (PMID 25668204, 2015). "Our results show that deafness related to ILDR1 deficiency is due to degeneration of cochlear outer hair cells (OHCs), the destruction of the tunnel of the organ of Corti, and abnormal expression of tricellulin and other hearing-related proteins." (PMID 25819842, 2015). "Whole-exome sequencing of a Korean multiplex family segregating partial deafness identified a novel homozygous ILDR1 variant (p.P69H) within the Ig-like domain." (PMID 25668204, 2015). "Here we show that two different mouse Ildr1 mutant alleles have early-onset severe deafness associated with a rapid degeneration of cochlear hair cells (HCs) but have a normal endocochlear potential." (PMID 25217574, 2015). "It has been mostly reported that ILDR1 mutations are associated with hearing loss or deafness." (PMID 37435641, 2024). "However, only single heterozygous variant in USH2A and ILDR1 was identified, thus, the single variant cannot cause deafness in the patient." (PMID 31478598, 2019). "To further elucidate the mechanism of deafness related to ILDR1 deficiency, we used a differential proteomic approach (LC-MS/MS) to comprehensively assess differential protein expression in the cochleae of Ildr1+/− and Ildr1−/− mice at P21." (PMID 25819842, 2015). "Is human deafness due to mutations of ILDR1 nonsyndromic or syndromic?" (PMID 25217574, 2015). "Given these in vivo findings, it is also possible that the mutation within ILDR1 may lead to deafness via a different mechanism unrelated to failed tricellulin recruitment at TCs, or through a combination of these mechanisms." (PMID 25668204, 2015). "Systematic exclusion of the variants either in the homozygous or compound heterozygous state from 10 autosomal genes based upon a segregation study among family members of SNUH23 indicated that the p.P69H allele of ILDR1 most likely accounts for the partial deafness in this family." (PMID 25668204, 2015). "Mutations of ILDR1 cause human autosomal recessive deafness DFNB42." (PMID 25822906, 2015). "Additionally, we provide insight into potential mechanisms for deafness due to the loss of ILDR1 function." (PMID 25217574, 2015). "ILDR1-dependent ARNSHL known as deafness, autosomal recessive 42 (OMIM# 609,646), is considered a rare sub-type of HL mostly reported in families of Middle-Eastern origin." (PMID 40100472, 2025). "Mutations in junctional proteins concentrated at support cell-hair cell TJs, including claudin 14, tricellulin, and angulin-2/ILDR1, cause deafness." (PMID 34458255, 2021). "Three known deafness genes, including SMPX, USH2A, and ILDR1, were identified, in which the variants in SMPX and USH2A were predicted to have a high‐to‐medium high impact on the function." (PMID 31478598, 2019). "Based on sequencing results of ILDR1 and other deafness genes in chromosome 3, F1-II-1 and F2-II-1 has a distinct genotype for a number of SNPs, suggesting that those two probands were not closely related." (PMID 29849566, 2018). "In fact, all knockout mice unable to express ILDR1 intracellular domain showed severe to profound deafness." (PMID 28945813, 2017). "Tricellulin and ILDR1 are localized at the tTJ and alterations in these proteins have been reported to be involved in deafness." (PMID 27195292, 2016). "The onset of hair cell degeneration in Ildr1 null mice was earlier than that in the reported Tric mutant mice, which mimic one of the tricellulin mutations in DFNB49 deafness." (PMID 25822906, 2015).
deafness (continued). "Among down-regulated proteins in the Ildr1−/− mice, some have a close relationship with hearing development and deafness." (PMID 25819842, 2015). "This novel ILDR1 mutant allele is associated with weakened localization of angulin-2/ILDR1 at TCs, as well as a milder auditory phenotype compared with the originally reported DFNB42 profound deafness phenotype." (PMID 25668204, 2015). "We report that Ildr1 null mice exhibit deafness and postnatal hair cell degeneration in the cochlea." (PMID 25822906, 2015). "To further elucidate the mechanism of deafness related to ILDR1 deficiency, we pursued a differential proteomic approach to comprehensively assess differential protein expression in the cochleae of Ildr1+/− and Ildr1−/− mice at P21." (PMID 25819842, 2015). "Functional compensation for the loss of ILDR1 in ILDR1 null mice does not occur since Ildr1 homozygous mutant mice exhibit profound deafness suggesting a unique function for ILDR1 at tTJs." (PMID 25217574, 2015). "Taken together, our data provide insight into the pathophysiology of human DFNB42 deafness and demonstrate that ILDR1 is crucial for normal hearing by maintaining the structural and functional integrity of tTJs, which are critical for the survival of auditory neurosensory HCs." (PMID 25217574, 2015). "The function of ILDR1 in hearing is largely unknown, and the molecular mechanisms of ILDR1 in deafness remain to be elucidated." (PMID 25819842, 2015). "Twelve homozygous mutations in known deafness genes, of which eight are novel, were identified in 12 families: MYO15A-p.Q1425X, -p.S1481P, -p.A1551D; LOXHD1-p.R1494X, -p.E955X; GIPC3-p.H170N; ILDR1-p.Q274X; MYO7A-p.G2163S; TECTA-p.Y1737C; TMC1-p.S530X; TMPRSS3-p.F13Lfs*10; TRIOBP-p.R785Sfs*50." (PMID 23226338, 2012). "The most frequent causative deafness gene was TMC1 (DFNA36) (3 cases), followed by the next tier of genes (2 cases each) (CDH23, COCH, SLC26A4, TMPRSS3, ATP1A3), and the genes that were detected only once (ACTG1, GJB2, ILDR1, MYO7A, MYO15A, NF2, NLRP3 and SERPNB6)." (PMID 32238869, 2020). "Taken together, these previous observations suggest the hypothesis that the mislocalization of tricellulin by the lack of angulin-2/ILDR1 around hair cells is the cause of deafness with hair cell degeneration in Ildr1k-/- mice." (PMID 25822906, 2015). "This incomplete recruitment of tricellulin due to partial mislocalization of angulin-2/ILDR1 could be a direct cause of progressive partial deafness in the patients described in this study since mislocalization of tricellulin causes deafness in humans and mice regardless of angulin-2/ILDR1." (PMID 25668204, 2015). "Taken together, our data suggest that ILDR1 is important for the survival of OHCs and provide novel insights into the pathogenesis of human deafness DFNB42 deafness." (PMID 25819842, 2015). "Interestingly, both Ildr1 KO mouse models manifested in deafness, suggesting that the models are not essentially different from each other." (PMID 32587380, 2020). "We found that Ildr1 knockout mice showed no detectable phenotype other than deafness." (PMID 32587380, 2020).
hearing loss (12 papers, 2015 to 2025). "This study is the largest GWAS meta-analysis of ARHI to date and identified 7 associated loci, of which 5 are novel (FXYD5, IPP, SPIRE2, SPTBN1 and TRIL) and 2 have been previously related to hearing loss (ILDR1, ISG20)." (PMID 31645637, 2019). "The novel p.G141R mutation in ILDR1 is the likely genetic cause for the hearing impairment in two unrelated Chinese Han DFNB42 families." (PMID 29849566, 2018). "ILDR1 associated hereditary hearing impairment is very rare and this is the first report of identifying a loss-of-function mutation in ILDR1 gene associated with hereditary hearing impairment in Chinese population." (PMID 30804975, 2019). "Additionally, a recent report on ILDR1-knockout mouse models demonstrated the progressive degradation of outer hair cells and organ of Corti, further supporting the progressive hearing loss disorder phenotype." (PMID 28713423, 2017). "In Saudi Arabia, several gene mutations (e.g., GIPC3, ILDR1, W77R, MYO15A, TMC1, TMPRSS3, and DFNB67) have been identified in families and are associated with childhood hearing loss." (PMID 40918669, 2025). "Mutations in hereditary deafness genes, such as TRIOBP, ILDR1, and EYA4, also exhibited significant correlations with age-related hearing impairment." (PMID 37062025, 2023). "Association between germline mutation in ILDR1 gene and ARNSHL has been confirmed again for patients with hearing loss in both the Saudi-Arabian and the Iranian populations." (PMID 30804975, 2019). "This analysis confirmed the underlying variability of clinical phenotype in ILDR1-dependent hearing loss, and additionally supported the possibility of DFNB42 being a progressive hearing loss disorder, successfully treatable by CI." (PMID 28713423, 2017). "Mutations in ILDR1 are responsible for DFNB42, but the pathogenesis of hearing loss caused by ILDR1 mutations remains to be elucidated." (PMID 25819842, 2015). "For instance, at the 3q13.3 risk locus our approach excludes a strong positional candidate, ILDR1, in which loss-of-function variants cause a recessive hearing loss disorder, since none of the risk variants at this locus were predicted to alter ILDR1 function." (PMID 32986727, 2020). "This truncated and non-functional ILDR1 protein unable to recruit tricellulin followed by malformation of tight junctions which finally renders the normal function of auditory hair cells and causes hearing impairment." (PMID 30804975, 2019). "Potential causative variants were identified in genes associated with nonsyndromic hearing loss (CIB2, COL11A1, ILDR1, MYO15A, TMPRSS3, and WFS1), nonsyndromic hearing loss or Usher syndrome (CDH23, MYO7A, PCDH15, and USH2A), and other syndromic forms of hearing loss (CHD7, OPA1, and SPTLC1)." (PMID 34837038, 2022).
autosomal recessive hearing loss (7 papers, 2015 to 2025). "Mutations in TRIC (tricellulin) and ILDR1 (angulin-2/ILDR1) have been associated with autosomal recessive nonsyndromic deafness DFNB49 and DFNB42 (MIM 609646), respectively." (PMID 38525683, 2024). "Several mutations within the ILDR1 gene have been associated with autosomal recessive nonsyndromic hearing loss to variable extent." (PMID 31645637, 2019). "Among the genes encoding these proteins, mutated TRIC (tricellulin) and ILDR1 (angulin-2/ILDR1) have been reported to cause autosomal recessive nonsyndromic deafness DFNB49 (MIM 610153) and DFNB42 (MIM 609646), respectively." (PMID 25668204, 2015). "Previously reported recessive mutations within ILDR1 have been shown to cause severe to profound nonsyndromic sensorineural hearing loss (SNHL), DFNB42." (PMID 25668204, 2015).
nonsyndromic deafness (2 papers, 2015 to 2017). An auditory system disease that is associated with permanent hearing loss caused by damage to structures in the inner ear and/or the middle ear, which is not associated with other signs and symptoms. "Consistently, LSR has two homologous genes known as ILDR1 and ILDR2, of which mutations in ILDR1 result in familial nonsyndromic deafness." (PMID 28767685, 2017). "Our initial conclusion that mutations of human ILDR1 cause exclusively nonsyndromic deafness DFNB42 may have to be revised as we learn more about the physiological consequence of a loss of ILDR1 in mouse." (PMID 25217574, 2015).
3M syndrome (1 paper, 2023). 3M syndrome is a primordial growth disorder characterized by low birth weight, reduced birth length, severe postnatal growth restriction, a spectrum of minor anomalies (including facial dysmorphism) and normal intelligence. "Another case report described developmental delay, and hearing loss in a patient with 3M syndrome due to co-existence variants in CUL7 and ILDR1 gene." (PMID 37520055, 2023).
age-related hearing impairment (1 paper, 2019). "Especially the ILDR1 gene is a high profile candidate, as it contains our top SNP, is a known hearing loss gene, has been linked to age-related hearing impairment before, and in addition is preferentially expressed within hair cells of the inner ear." (PMID 31645637, 2019).
hearing (1 paper, 2015). "To determine if Idlr1 knockout mice also exhibited a hearing impairment phenotype that mimicked the phenotype of DFNB42, we measured the ABR hearing thresholds in Ildr1+/− and Ildr1−/− mice at P21." (PMID 25819842, 2015).
influenza (1 paper, 2022). An acute viral infection of the respiratory tract, occurring in isolated cases, in epidemics, or in pandemics; it is caused by serologically different strains of viruses (influenzaviruses) designated A, B, and C, has a 3-day incubation period, and usually lasts for 3 to 10 days. "Moreover, we examined the effect of ILDR1 overexpression on virus infection, and confirmed that virus replication was significantly promoted and the viability of virus-infected cells is decreased, suggesting that ILDR1 might play a role in influenza virus replication." (PMID 35595813, 2022).
lymphoma (1 paper, 2015). A malignant (clonal) proliferation of B- lymphocytes or T- lymphocytes which involves the lymph nodes, bone marrow and/or extranodal sites. "Immunoglobulin-like domain containing receptor 1 (ILDR1) is a poorly characterized gene that was first identified in lymphoma cells." (PMID 25819842, 2015).
myeloma (1 paper, 2018). "While ILDR1 expression was detected in various cell lines, including the U266 myeloma line, expression in primary cells and hematopoietic malignancies has not been surveyed." (PMID 30540814, 2018).
non-Hodgkin lymphoma (1 paper, 2022). Distinct from Hodgkin lymphoma both morphologically and biologically, non-Hodgkin lymphoma (NHL) is characterized by the absence of Reed-Sternberg cells, can occur at any age, and usually presents as a localized or generalized lymphadenopathy associated with fever and weight loss. "Immunoglobulin-like domain-containing receptor 1 (ILDR1) was first identified in a screen for genes likely to be involved in the progression of non-Hodgkin’s lymphoma." (PMID 35749484, 2022).
periodontitis (1 paper, 2024). An acute or chronic inflammatory process that affects the tissues that surround and support the teeth. "We found that the allele loci of NPHS1(rs114615449), ILDR1(rs142746163), and DMXL2(rs3078066) showed significant differences between the severe periodontitis patients and dbSNP 155 (East Asian race) (P < 0.05)." (PMID 37435641, 2024). "In this study, our correlation analysis with dbSNP showed that ILDR1 and NPHS1 were associated with severe periodontitis (P < 0.05)." (PMID 37435641, 2024). "The allele frequencies at the mutation loci of LFNG, LENG8, NPHS1, HFE, ILDR1, and DMXL2 genes were analyzed in the 15 patients with severe periodontitis." (PMID 37435641, 2024).
Polydipsia (1 paper, 2020). Excessive thirst manifested by excessive fluid intake. "It has been shown that growth retardation, polydipsia and polyuria were manifested in Ildr1 KO mice due to a defect of urine concentrating mechanisms." (PMID 32587380, 2020).
swine influenza virus (1 paper, 2025). "In addition, Plscr1 competes with immunoglobulin-like domain-containing receptor 1 (ILDR1) for NP binding, inhibiting swine influenza virus (SIV) infection in mice." (PMID 41439508, 2025).
virus infection (1 paper, 2022). "ILDR1 is highly expressed in the lungs, and its expression level is increased after virus infection." (PMID 35595813, 2022). "The expression level of ILDR1 is increased after virus infection and as an antiviral suppressor to inhibit viral replication." (PMID 35595813, 2022). "The results show that ILDR1 expression is up-regulated after viral infection in Plscr1−/− mice, suggesting that ILDR1 might play a role in Influenza virus infection." (PMID 35595813, 2022).
cancer (2 papers, 2012 to 2019). A tumor composed of atypical neoplastic, often pleomorphic cells that invade other tissues. "ILDR1 was identified as a diagnostic marker for cancer progression." (PMID 31552087, 2019).
infection (1 paper, 2022). The state of being infected such as from the introduction of a foreign agent such as serum, vaccine, antigenic substance or organism. "Western blot results show that ILDR1 level is significantly increased by more than 15-fold on the first day after infection and then decreases as the viral load decreases." (PMID 35595813, 2022). "The results showed that ILDR1 levels significantly increased by more than 15-fold on the first day after infection and it decreased as the viral load decreased." (PMID 35595813, 2022). "ILDR1 is weakly expressed in the lungs of mice before infection, while a substantial increase of ILDR1-positive cells was observed at 3 dpi." (PMID 35595813, 2022).
ILDR1 also shares sentences with these, for which no sentence is quoted: Hearing impairment (3 papers); age (1); developmental delay (1); Hyperglycemia (1); hypothyroidism (1); Obesity (1); Polyuria (1); Tinnitus (1); tumor (1); Usher syndrome (1).